GSTM1 (glutathione S-transferase mu 1)
Diseases named in the same sentence as GSTM1 in open-access papers (continued):
Sharing a sentence is not in itself a finding about the gene and the disease.
tumor (continued). "GSTT1 polymorphism correlated with higher tumor grade in CRC patients (p = 0.035), and the GSTM1 null/null genotype was associated with more frequent metastasis to lymph nodes (pN classification, p = 0.036)." (PMID 29765533, 2018). "Many tumor studies focus on three of the eight transferase classes, namely theta (θ), mu (μ), and pi (π), encoded by genes GSTT1, GSTM1, and GSTP1, respectively." (PMID 29765533, 2018). "GSTT1 polymorphism correlated with higher tumor grade in CRC patients, and the GSTM1 null/null genotype was associated with more frequent metastasis to lymph nodes (pN classification)." (PMID 29765533, 2018). "In this small, yet novel, case-only study of genetic risk factors for GIST tumor subtypes we identified several variants in CYP1B1, RAD23B, GSTM1, and ERCC2 that we believe are worthy of further investigation." (PMID 23637977, 2013). "The proportion of males in the multiple BCC group (61.3%) was greater than in controls (47.0%) and single BCC (52.2%), and the frequency of the combination GSTM1 null/male gender was significantly greater in patients with multiple tumours (P = 0.002)." (PMID 8554981, 1996). "The mRNA expression of CCND1 and CYP2S1 genes was high in COAD tumor tissues, while the mRNA expression of GSTM1 gene was low in COAD tumor tissues, and the difference was statistically significant, which was consistent with the previous results of TCGA database and GEPIA2 data analysis." (PMID 36203457, 2022). "Since STAT3 has been shown to be a molecular hub and plays a significant role in GBM tumor progression, we further examined whether knockdown of GSTM1 significantly decreased phosphorylated STAT3 (STAT3-pSer727) levels." (PMID 34732244, 2021). "The statistics of high GSTM1 staining were shown in tumor tissues versus normal tissues." (PMID 34732244, 2021). "The presence of the GSTM1 null genotype is associated with increased risk for HNSCC, while the GSTT1 null genotype and the A313G GSTP1 polymorphism contribute to decreased risk for this tumor type." (PMID 32592358, 2020). "A further multivariate analysis demonstrated that lymph node status (P < .001), tumor size (P < .001), IHC‐based subtype (P < .001), chemotherapy or not (P < .001), and GSTM1‐null/present polymorphism (P = .02) were significant independent factors for RFS." (PMID 30032483, 2018). "Predominant expression of the GSTP1 subclass (compared to GSTT1 and GSTM1) in colorectal epithelial and tumour tissue may explain in part this phenomenon." (PMID 15213713, 2004). "GSTM1 phenotype distribution depends on age, smoking habit and tumour pathology." (PMID 7640212, 1995). "In this study, we only identified JHU029 as a BAA-derived HNSCC cell line, but it is critical to recognize that the differential tumor inhibitory effect of GSTM1 knockdown between JHU029 and two HNSCC cell lines derived from white individuals (HN12 and SCC9), may depend on the cellular context." (PMID 39044272, 2024). "Consequently, the F2P Score was established based on the combination of six genomic variables (ESR1, PGR, CD68, BAG1, BCL2, and GSTM1) and two clinicopathological variables (age and categorical tumor size) with the shrinkage factors of 0.314 and 0.888, respectively." (PMID 33042787, 2020). "Individuals with homozygous deletions of GSTM1 or GSTT1 lack GSTs and therefore may be unable to eliminate electrophilic carcinogens efficiently, which may increase the risk of somatic mutations that lead to tumor formation." (PMID 24250808, 2013). "In contrast to GSTM1, TSPAN8 was the only upregulated Black patient tumor specific gene that at high expression levels associated with an increase in the hazard ratio (1.81) and decrease overall survival by 7.5 months." (PMID 36812168, 2023). "Of note, we also found a high residual effect for GSTM1 and VIM, two genes known to support tumor progression and metastasis." (PMID 35565214, 2022).
tumor (continued). "Among them, CCND1, GSTM1 and CYP2S1 were differentially expressed in normal tissues and tumor tissues, while the other two genes had the same expression trend as the database analysis." (PMID 36203457, 2022). "To establish a direct link between GSTM1 and GSTM2 activity and tumor growth rate, we tested if their promoter methylation status is associated with the expression of the marker of proliferation Ki-67." (PMID 34871444, 2021). "Unsupervised hierarchical clustering analysis based on methylation pattern had identified two tumor clusters, which significantly differ by CpG island methylator phenotype (CIMP), tobacco, GSTM1, CYP1A1, HPV and survival status." (PMID 26098903, 2015). "GSTM2 is known to play a tumor suppressor role, and functional characteristics that may also be shared GSTM5; therefore, the effects of GSTM1-5 on cell viability were compared by overexpressing these proteins in 5637 cells." (PMID 33802702, 2021). "Low expression of GSTM1 and GSTM2 was related to favorable OS (adjusted P = 0.006, adjusted HR = 0.559, 95% CI = 0.367–0.849 and adjusted P = 0.002, adjusted HR = 0.519, 95% CI = 0.342–0.790, respectively) after adjusting for tumor stage." (PMID 32539715, 2020). "GSTM1 and/or GSTT1 deletion produces an absence of enzymatic activity with an enhanced effect of chemotherapy treatment, greater oxidative damage in tumor cells and ensuingly higher toxicity, causing an expected probable increase in survival." (PMID 33273562, 2020). "As GSTM1 plays a role in inhibiting the activity of proliferation regulator MEKK, we proposed that it may act as a transducer in tumor growth signaling pathways." (PMID 25202346, 2014). "The expected model size with the highest performance level consists of 10 of the most robust predictive variables and is comprised of four clinico-pathological variables and six additional proteins: nodal status, tumor size, AURKA, BCL2, age, CD68, HER2, MYBL2, CCNB1 and GSTM1." (PMID 20809974, 2010). "In addition, GSTA1, GSTM1, and GSTZ1 are reported to be downregulated in tumor tissue and can correlate with a poor prognosis, while GSTT1, GSTO1, and GSTK1 are mostly reported to be upregulated in tumor tissue compared to the normal surrounding tissue." (PMID 33228209, 2020). "Unlike other diseases such as neoplasms in which GSTM1 and GSTT1 polymorphisms are extensively investigated, there are few studies that investigate the association between GSTM1, GSTT1, and GSTP1 gene variants and the presence of microvascular complications in T1DM and T2DM." (PMID 26435566, 2015). "According to this analysis, there was a statistically significant increase in level of expression of GSTM1 and TSPAN8, but not GAGE12J and SNORD59B in the tumor tissue samples obtained from Black patients." (PMID 36812168, 2023). "The absence of GSTM1 and GSTT1 compromise the detoxification of these high levels of catechol estrogens, which eventually will contribute to tumor development in later ages." (PMID 33513690, 2021). "However, hormone-related genes (BAG1, BCL2, CD68, ESR1 (ER), GSTM1, PGR, SCUBE2) do not show significant differential expression among all tumor samples." (PMID 38254834, 2024).
infection (11 papers, 2014 to 2025). The state of being infected such as from the introduction of a foreign agent such as serum, vaccine, antigenic substance or organism. "Nine down-regulated DEGs were commonly downregulated in response to either Aβ pathology or MA10 infection (Vegfa, Atp1a2, Slc6a11, Gja1, Slc6a11, Gpr37l1, Plpp3, Gstm1, Agt)." (PMID 41497643, 2025). "For the GSTM1 wildtype, more enriched pathways were found which were also affecting a broader spectrum of biological functions, such as pathways involved in ‘disease,’ ‘infection,’ ‘transcription,’ ‘translation’, and ‘signaling’." (PMID 38337709, 2024). "Of these, four, C-C Motif Chemokine Ligand, CCL3L3; mitochondrial Glutathione-S-Transferase, GSTM1, F8A3 and F8A2, are directly related to the interrelated processes of infection, inflammation, endosomal motility, and ROS metabolism." (PMID 33972602, 2021). "Overall, CMA3p20 infection of BALB/c mice caused a significant decrease in the expression of the AOE genes in the lung tissue, specifically Cat, Gstm1, and Prdx6, while it did not affect Sod1 and Prdx1." (PMID 37022178, 2023).
kidney disease (10 papers, 2013 to 2024). "GSTM1 (Glutathione S-Transferase Mu 1) encodes a member of a superfamily of antioxidant enzymes, which is important in kidney disease progression." (PMID 37403156, 2023). "Several lines of evidence indicate an association between the GSTM1*0/0 genotype and faster progression of kidney disease as well as worse outcome of dialysis patients." (PMID 24423050, 2014). "Loss of GSTM1 gene could inhibit kidney disease progression; and GSTM1 and GSTT1 prevent renal cell injury due to carcinogens." (PMID 29137244, 2017). "Deletion polymorphisms of GSTM1 and GSTT1, members of the glutathione S-transferase family, are common in humans and are presumed to be associated with various kidney diseases." (PMID 39386217, 2024). "Dietary supplementation of sulforaphane-rich broccoli powder ameliorated kidney disease only in Gstm1 KO mice." (PMID 33477669, 2021). "In summary, this cross-sectional study does not support some earlier observations that GSTM1 inactive genotype is a risk factor for kidney disease in Black individuals." (PMID 35967115, 2022). "There is also the possibility that GSTM1 may only be deleterious when GFR falls below certain levels or in the setting of specific types of kidney disease." (PMID 31555322, 2019).
adenocarcinoma (5 papers, 2006 to 2021). A common cancer characterized by the presence of malignant glandular cells. "A previous meta-analysis for Chinese populations presented higher risks of LC with GSTM1 deletion for SCC and adenocarcinoma (AC) than the small cell (SC) LC types." (PMID 30123431, 2018).
cardiovascular diseases (5 papers, 2020 to 2025). "The increase of cardiovascular disease-related marker associated with air pollutant exposure in individuals with GSTM1 null genotype suggest that individuals with deletion of GSTM1 is more prone to develop air pollutant induce cardiovascular." (PMID 36793931, 2023). "In the case of cardiovascular diseases, the differences in the influence of GSTM1, GSTT1, GSTP1 and GSTA1 polymorphisms on their development or lack of it depending on the continent were shown." (PMID 37819495, 2023). "Association between GSTM1 and GSTT1 polymorphisms and cardiovascular disorders has long been studied." (PMID 32188413, 2020). "With respect to the role of MCP-1 in attracting monocytes to the site of vascular injury, our results provide one of the mechanistic clues for higher risk of cardiovascular diseases in subjects lacking GSTM1 (GSTM1-null genotype), which is even more pronounced in uremic milieu in ESRD patients." (PMID 33574979, 2021).
inflammation (3 papers, 2012 to 2023). Aberrant reaction of the microcirculation characterized by movement of fluid and leukocytes from the blood into extravascular tissues. "This in vitro study using primary human bronchial epithelial cells provides experimental evidence in support of the notion that the GSTM1 null phenotype is a risk factor for DEP-induced airway inflammation." (PMID 22867088, 2012). "We have demonstrated that the glutathione S-transferase M1 (GSTM1) null genotype could aggravate DEP-induced airway inflammation in human subjects." (PMID 22867088, 2012).
lung (3 papers, 2017 to 2024). "The results of the present study highlight the association between oxidative stress, programmed cell death, and the GSTM1 gene in the development of lung carcinogenesis." (PMID 37143928, 2023).
neurodegenerative disease (3 papers, 2017 to 2022). A disorder of the central nervous system characterized by gradual and progressive loss of neural tissue and neurologic function. "GSTM1 in astrocytes may also be involved in aging-associated changes in the brain and possibly aging-associated neurodegenerative diseases." (PMID 36685285, 2022). "As we find abundant GSTM1 expression in astrocyte-like cells in AD and FTD post-mortem brain tissue, astrocytic GSTM1 upregulation may be present across neurodegenerative diseases." (PMID 35713703, 2022).
peripheral neuropathy (3 papers, 2013 to 2023). A disorder affecting the peripheral nervous system. "A statistically significant association between the incidence of peripheral neuropathy higher than grade 2 and the GSTP1-105 (P=0.03) and GSTM1 genotypes (P=0.02) was identified by multivariate logistic regression analyses." (PMID 24137384, 2013). "GSTP1-105 and GSTM1 genotypes may be useful markers of severe peripheral neuropathy in MCRC patients treated with 5-FU/oxaliplatin as first-line chemotherapy." (PMID 24137384, 2013). "In the present study, correlations were identified between the polymorphism patterns of TS, MTHFR, ERCC1, ERCC2, GSTP1, GSTT1 and GSTM1 and the clinical outcome, including the incidence of peripheral neuropathy, in Japanese MCRC patients who were treated with modified FOLFOX6 (mFOLFOX6)." (PMID 24137384, 2013). "However, GSTP1-105 and GSTM1 genotypes may be more useful as markers for severe oxaliplatin-induced peripheral neuropathy in Japanese patients compared with Western patients." (PMID 24137384, 2013). "Gene alterations, such as GSTP1 and GSTM1, glutathione-S-transferase genes and voltage-gated sodium channel genes SCN4A, SCN9A and SCN10A, together with pre-existing peripheral neuropathy have been demonstrated to be the principal risk factors for OIPN onset." (PMID 33671327, 2021). "In agreement with previous studies, the incidence of peripheral neuropathy higher than grade 2 was identified to significantly correlate with the GSTP1-105 and GSTM1 genotypes." (PMID 24137384, 2013). "A statistically significant correlation between the incidence of peripheral neuropathy higher than grade 2 and the GSTP1-105 (P=0.03) and GSTM1 (P=0.02) genotypes was determined using multivariate regression analysis." (PMID 24137384, 2013). "The incidence of peripheral neuropathy of grades 2 (n=42) and 3 (n=2) was found to significantly correlate with the GSTP1-105 (P=0.05) and GSTM1 (P=0.03) genotypes, as identified by univariate regression analyses." (PMID 24137384, 2013). "Individuals who were GSTM1-negative also had peripheral neuropathy, whereas individuals who were GSTM1-positive did not." (PMID 24137384, 2013).
hematological disorders (2 papers, 2018 to 2022). "The results of this study showed that, individuals carrying null GSTT1 or both null STT1 and GSTM1 genotypes had a higher risk and were more susceptible to benzene-induced hematological disorders." (PMID 29204680, 2018). "Similarly, subjects with both null GSTT1 and GSTM1 had a significantly higher risk for hematological disorders as compared to subjects with positive GSTT1 and GSTM1 genotypes (OR 2.35, 95% CI 1.14–4.8)." (PMID 29204680, 2018). "Several previous studies focused on a possible association between the genetic polymorphism of GSTM1 and GSTT1 genes and the risk of blood disorders in persons occupationally exposed to benzene." (PMID 29204680, 2018). "Moreover, the result showed that, subjects carrying both null GSTT1 and GSTM1 genotypes had higher risk of hematological disorders compared to subjects with both positive GSTT1 and GSTM1 genotypes (OR = 2.35, CI = 1.14–4.8)." (PMID 29204680, 2018). "Moreover, subjects with both null GSTT1 and GSTM1 genotypes had a significantly higher risk for hematological disorders as compared to subjects with positive GSTT1 and GSTM1 genotypes (OR 2.35, 95% CI 1.14–4.8)." (PMID 29204680, 2018).
metabolic disease (2 papers, 2014 to 2024). A congenital disorder (due to inherited enzyme abnormality) or acquired (due to failure of a metabolically important organ) disorder resulting from an abnormal metabolic process. "The GSTM1 null and GSTT1 null genotypes have been reported to be associated with the risk of cardiovascular or metabolic diseases, including NAFLD, in the general population." (PMID 25372290, 2014).
respiratory disease (2 papers, 2007 to 2022). "Two prevalent homozygous gene deletions of the Mu-1 and Theta-1 GST members (GSTM1 and GSTT1) have repeatedly been associated with increased susceptibility to respiratory disease and lung function deficits in children, asthmatics, and smokers with respiratory symptoms." (PMID 17217536, 2007).
retinopathy (1 paper, 2013). "While t he statistical analysis between GSTM1 and retinopathy show significant association (p = 0.04) that confirm the effect of free radical in T2DM in other studies." (PMID 24355557, 2013). "Finally, the statistical analysis between GSTT1 and GSTM1 interaction in retinopathy show weak significant association (p = 0.052)." (PMID 24355557, 2013). "Genotyping of GSTM1 revealed that among these 57 patients with retinopathy, 26 patients (45.6%) showed null genotype while 31 patients (54.4%) were positive for GSTM1 gene." (PMID 24355557, 2013). "But is inconsistent with the only study that show GSTM1 null genotype might confer protection against retinopathy in Caucasians with T2DM." (PMID 24355557, 2013). "Significant correlation between GSTM1 null genotype and retinopathy in this and other studies could indicate this fact that impair cellular metabolism result in increase free radicals and oxidative pressure." (PMID 24355557, 2013). "In this study deletion of GSTT1 and GSTM1 genes in 57 diabetics’ patients with retinopathy and 58 diabetic peoples without retinopathy was examined." (PMID 24355557, 2013). "Among 58 diabetic patients without retinopathy, 38 patients (65.5%) had null genotypes and 20 patients (34.5%) were positive for GSTM1 gene." (PMID 24355557, 2013).
GSTM1 also shares sentences with these, for which no sentence is quoted: end-stage renal disease (6 papers); Insulin resistance (4); neutropenia (4); Anxiety (3); brain tumors (3); chronic periodontitis (3); essential hypertension (3); neurological disorders (3); presbycusis (3); apical periodontitis (2); cystic fibrosis (2); depression (2); emphysema (2); fibrosis (2); gastrointestinal tumor (2); gynecological cancer (2); ischemic stroke (2); lung fibrosis (2); medulloblastoma (2); Multiple Myeloma (2); nasal polyps (2); non-alcoholic fatty liver disease (2); oligospermia (2); oral cavity squamous cell carcinoma (2); resistant hypertension (2); stomach cancer (2); thyroid nodule (2); type 1 diabetes (2); age (1); Airway obstruction (1).
A further 89 diseases each share a sentence with GSTM1 in 1 paper.